RBP4 (retinol binding protein 4)
Diseases named in the same sentence as RBP4 in open-access papers (continued):
Sharing a sentence is not in itself a finding about the gene and the disease.
lipid metabolism disorder (1 paper, 2025). "Germacrone can protect the liver by inhibiting the Nrf2/Rbp4 signaling pathway, improving oxidative stress and lipid metabolism disorder in the ALD model." (PMID 40442809, 2025). "This study aims to explore the therapeutic effect of Germacrone on ALD and further reveal the molecular mechanism of Germacrone’s improvement of oxidative stress and lipid metabolism disorder by regulating the Nrf2/Rbp4 signaling pathway." (PMID 40442809, 2025). "Our experimental data demonstrate that Germacrone has a significant hepatoprotective effects against ALD by regulating the Nrf2/Rbp4 signaling pathway to improve liver lipid metabolism disorders and oxidative stress damage." (PMID 40442809, 2025). "To summarize, this study revealed the molecular mechanism of Germacrone in improving oxidative stress and lipid metabolism disorder in ALD through inhibition of the Nrf2/Rbp4 pathway, using integrated in vivo and in vitro experimental systems." (PMID 40442809, 2025). "The discovery further refine our understanding of the Nrf2/Rbp4 signaling pathway in lipid metabolism disorder and oxidative stress imbalance and provides a new perspective and molecular target for the study of the pathological mechanism of ALD." (PMID 40442809, 2025). "In addition to Nrf2, Rbp4 (retinol-binding protein 4) has also been recognized as an important regulator of lipid metabolism disorders in recent years." (PMID 40442809, 2025).
mastitis (1 paper, 2022). Inflammation of breast tissue during lactation or postpartum due to an obstructed duct or infection. "However, we found that APOA1, APOA4, APOE, and RBP4 were downregulated during clinical mastitis." (PMID 36335251, 2022).
medullary thyroid carcinoma (1 paper, 2019). "RBP4 is an adipokine that is mainly produced by adipose tissue and its serum levels in medullary thyroid carcinoma patients are not significantly different from those that are found in healthy individuals." (PMID 30813269, 2019).
memory impairment (1 paper, 2021). "We found a decrease in plasma RBP4 in aged animals without memory impairment." (PMID 34417282, 2021). "Here, we measured plasma RBP4 and protein levels of hippocampal STRA6 receptor, RA synthesizing and catabolizing enzymes, RARα, FMRP, and GluR1 in young (Y) rats and aged animals with and without memory impairment." (PMID 34417282, 2021).
meningioma (1 paper, 2014). A generally slow growing tumor attached to the dura mater. "Receiver operating characteristic (ROC) curve analysis was carried out to evaluate the individual performance of 4 proteins; HPX, Apo E and A-I, RBP4 for prediction of different grades of meningiomas." (PMID 25413266, 2014). "On the other hand, differential expression of RBP4 was found to be significant only in the grade II meningioma patients." (PMID 25413266, 2014). "Hemopexin (HPX), apolipoprotein E and A-I (Apo E and A-I), and plasma retinol binding protein (RBP4) concentrations were directly measured in the serum samples of healthy controls and meningiomas patients (MGI, MGII and MGIII) using ELISA." (PMID 25413266, 2014).
Menstrual disorder (1 paper, 2025). Category of disorders related to menstruation. "Contrary to expectations, we did not observe a significant association between RBP-4 levels and lipid metabolism parameters in girls with menstrual disorders." (PMID 41303021, 2025).
mesothelioma (1 paper, 2025). A usually malignant and aggressive neoplasm of the mesothelium which is often associated with exposure to asbestos. "RBP4 acts as a protective gene in KIRP, LIHC, and mesothelioma (MESO), while it is a high-risk factor in HNSC, ovarian serous cystadenocarcinoma (OV), sarcoma (SARC), and UCEC." (PMID 41301068, 2025).
metastatic tumors (1 paper, 2020). "Moreover, our animal studies on two sister cell lines, nonmetastatic 67NR and metastatic 4T1, confirmed significantly higher RBP4 plasma levels in mice bearing metastatic tumors than in mice bearing nonmetastatic tumors." (PMID 32156052, 2020).
myopia (1 paper, 2025). "Apo A-I has been implicated as an atRA binding protein in the eye in myopia, wheras RBP4, a known chaperone for all-trans-retinol, which is known to bind retinol and atRA with similar binding affinity may facilitate atRA transport before cellular uptake." (PMID 40586643, 2025).
Neurogenic bladder (1 paper, 2025). A type of bladder dysfunction caused by neurologic damage. "Our study demonstrated that patients with neurogenic bladder exhibit lower serum creatinine concentrations compared to the reference group, alongside higher levels of cystatin C, RBP4, and RBP4 standardized to creatinine excretion in urine." (PMID 40217967, 2025). "The results of our investigation showed that children with neurogenic bladder after MMC have significantly higher RBP4 urinary levels in comparison to the reference group." (PMID 40217967, 2025). "Based on these reports, it can be asserted that urinary RBP4 levels may serve as an early marker of kidney impairment in patients with neurogenic bladder." (PMID 40217967, 2025). "The urinary RBP4 level may be useful in assessing the storage phase in patients with neurogenic bladder." (PMID 40217967, 2025).
ovarian endometriosis (1 paper, 2023). A non-neoplastic disorder characterized by the growth of endometrial tissue in the ovaries. "Moreover, the protein expression of RBP4 was remarkably higher in ovarian endometriosis than in normal control." (PMID 37662927, 2023). "Specifically, the expression of KIR2DL4 was remarkably downregulated, while the expressions of PROK1, IGFBP1, RBP4, G2MB, KIR3DL1, and PRF1 were significantly upregulated in ovarian endometriosis." (PMID 37662927, 2023).
peripheral artery disease (1 paper, 2021). "We investigated the association of RBP4 and adiponectin with the presence of symptomatic peripheral artery disease (PAD) and their possible prognostic role in major adverse cardiovascular events (MACE)." (PMID 34758835, 2021).
Pleural effusion (1 paper, 2026). The presence of an excessive amount of fluid in the pleural cavity. "SHAP analysis identified the retinol-binding protein 4 level, M. pneumoniae cycle-threshold value, D-dimer level, fever duration before admission, C-reactive protein-to-albumin ratio, and presence of pleural effusion as key predictors." (PMID 42112459, 2026).
prostate (1 paper, 2022). "Elevated levels of RBP4 and cadherin-2 signal early stages of prostate carcinogenesis, while ENO1, T-kininogen 2 and IDH2 represent more advanced stages." (PMID 35886909, 2022). "However, it seems that age can decrease the levels of this protein (Cont2 vs. Cont1 and PCa2 vs. PCa1), suggesting that RBP4 may be a urinary biomarker for early stages of age-related prostate carcinogenesis." (PMID 35886909, 2022). "Thus, RBP4 content may reflect an attempt by epithelial cells to counteract prostate carcinogenesis when testosterone acts as a promotor (as is the case in this study)." (PMID 35886909, 2022).
prostate adenocarcinoma (1 paper, 2025). "Prostate adenocarcinoma (PRAD) exhibited the highest frequency of RBP4 alterations (2.83%), primarily amplification and deep deletion." (PMID 40004479, 2025).
prostatic neoplasm (1 paper, 2022). "Importantly, RBP4 secretion by the PPAT has not yet been evaluated and the possible effects of RBP4 on PCa and in the context of metabolic dysfunction-associated prostatic neoplasm formation is largely uninvestigated." (PMID 35406450, 2022).
protein-energy malnutrition (1 paper, 2018). A nutritional deficit that is caused by inadequate protein or calorie intake. "In addition, the binding of RBP4 to retinol and transthyretin (TTR) was affected by several factors (e.g. serum retinol, vitamin A intake, physical activity, protein-energy malnutrition, and liver and renal diseases)." (PMID 30038059, 2018).
psoriasis vulgaris (1 paper, 2023). Plaque psoriasis is the most common presentation of psoriasis. "Therefore, we performed this meta-analysis, aiming to evaluate the association between RBP-4 and psoriasis vulgaris more comprehensively." (PMID 37711744, 2023). "The merged data suggested that the RBP-4 levels in patients with psoriasis vulgaris after treatment were similar to the levels in control subjects (SMD = 0.14, 95%CI: −0.38, 0.66, p > 0.05)." (PMID 37711744, 2023). "For patients with psoriasis vulgaris, RBP-4 levels are elevated, and systematic treatment can lower these levels." (PMID 37711744, 2023). "All seven studies reported the levels of RBP-4 in patients with psoriasis vulgaris and in control subjects." (PMID 37711744, 2023). "Through meta-analysis, the results from different studies were merged, so a more solid conclusion can be made that levels of RBP-4 were significantly higher in patients with psoriasis vulgaris." (PMID 37711744, 2023). "From the comparison of levels in patients at baseline and in controls in the seven studies, we found that the levels of RBP-4 increased significantly in patients with psoriasis vulgaris compared with control subjects." (PMID 37711744, 2023). "In this study, we investigated the relationship between retinol binding protein-4 and psoriasis vulgaris through meta-analysis." (PMID 37711744, 2023). "We found that levels of RBP-4 were significantly higher in patients with psoriasis vulgaris, and for patients with systematic treatment, a significant decrease of RBP-4 level was shown." (PMID 37711744, 2023). "For patients with psoriasis vulgaris, the levels of retinol binding protein-4 are elevated, and systematic treatment can lower RBP-4 levels." (PMID 37711744, 2023). "The merged data suggested that the levels of RBP-4 were significantly higher in patients with psoriasis vulgaris (SMD = 0.61, 95%CI: 0.14, 1.07, p < 0.05)." (PMID 37711744, 2023). "Therefore, we assumed systematic treatment can lower levels of RBP-4 in patients with psoriasis vulgaris." (PMID 37711744, 2023). "The merged data suggested that the RBP-4 levels did not change significantly in patients with psoriasis vulgaris after treatment (SMD = -0.33, 95%CI: −0.84, 0.19, p > 0.05)." (PMID 37711744, 2023).
renal Fanconi syndrome (1 paper, 2022). "RBP4 presents in urine at extremely high concentrations and undergoes the most intense extraction (>104-fold above “normal range”) when the proximal tubules fail to reabsorb low-molecular-weight proteins (e.g., heavy tubular proteinuria in renal Fanconi syndrome, FS)." (PMID 36011513, 2022).
renal fibrosis (1 paper, 2023). A final common manifestation of a wide variety of chronic kidney diseases characterized by glomerulosclerosis and tubulointerstitial fibrosis. "Patients with T2D have elevated urinary excretion of markers of tubular injury (RBP-4, GST-π), renal fibrosis (Col1, Col4), and antifibrotic growth factors (BMP-7, HGF)." (PMID 36836700, 2023). "The results demonstrate that elevated urinary excretions of the markers of tubular injury (RBP-4, GST-π) and renal fibrosis (Col1, Col4), as well as HGF, an antifibrotic regulator, are associated with the albuminuric pattern of CKD in subjects with T2D." (PMID 36836700, 2023).
respiratory infections (1 paper, 2013). "Low retinol-binding protein-4 (RBP4) is associated with a high risk of respiratory infections in the general population." (PMID 24099047, 2013).
rhabdomyolysis (1 paper, 2024). Necrosis or disintegration of skeletal muscle often followed by myoglobinuria. "RBP4 is a small protein associated with proximal tubule dysfunction when found in the urine; it significantly increased 24 h following rhabdomyolysis." (PMID 38681142, 2024).
rheumatic diseases (1 paper, 2024). "Overall, the strong inflammatory effect of RBP4 and its synergic activity with IL1β might explain the contribution of certain metabolic diseases to the development of rheumatic diseases." (PMID 38275649, 2024). "Despite TLR4 being one of the most important receptors of the innate immunity and having a key role in the development of several rheumatic diseases, there are no studies on the specific effect and signalling of RBP4 on different articular cells like chondrocytes or synoviocytes." (PMID 38275649, 2024).
Rod-cone dystrophy (1 paper, 2017). An inherited retinal disease subtype in which the rod photoreceptors appear to be more severely affected than the cone photoreceptors. "Gross pathology, retinal histology and rod-cone dystrophy observed in rbpr2musc97 mutants, suggested that loss of Rbpr2 likely affects RBP4-ROL uptake resulting in decreased ocular retinoid production." (PMID 29176573, 2017).
tauopathies (1 paper, 2024). "Moreover, this present study observed a negative correlation between RBP-4 and t-tau, indicating the dual relevance to tauopathies, ALS, and CTE." (PMID 39063053, 2024).
thyroid disorders (1 paper, 2022). "Defining the role of FABP4, fetuin-A and RBP4 presents a promising direction for the prevention and treatment of metabolic consequences accompanying thyroid disorders." (PMID 35448487, 2022). "Alterations in circulating RBP4 levels accompanying thyroid disorders were demonstrated." (PMID 35448487, 2022). "Therefore, therapies targeting FABP4, fetuin-A and RBP4 may prove to be effective means of counteracting metabolic complications in thyroid disorders." (PMID 35448487, 2022).
transthyretin amyloidosis (1 paper, 2025). "In our study, humanized RBP4/TTR mice (mice with humanized transthyretin and retinol binding protein 4) and RBP4/TTRVal50Met mice (mice with hereditary transthyretin amyloidosis) were established and divided into three groups by different genotypes and treatment strategies." (PMID 40765557, 2025).
triple-negative breast carcinoma (1 paper, 2025). An invasive breast carcinoma which is negative for expression of estrogen receptor (ER), progesterone receptor (PR), and human epidermal growth factor receptor 2 (HER2). "We studied these proteins, especially RBP4 and RBP7, to learn how their levels differ across cancers and what that means for patients, with special attention to triple-negative breast cancer, a difficult-to-treat subtype." (PMID 41301068, 2025). "Additionally, single-cell RNA sequencing (scRNA-seq) was used to analyze the expression of RBP4 and RBP7 in triple-negative breast cancer (TNBC), revealing their distribution across various cell types within the tumor microenvironment." (PMID 41301068, 2025). "Our comprehensive analysis, using bioinformatics tools and experimental validations, revealed distinct expression profiles of RBP family members across various cancers, highlighting the critical role of RBP4 and RBP7 in the context of triple-negative breast cancer biology." (PMID 41301068, 2025).
Urea (1 paper, 2022). "Urea increased ROS levels and expression of the adipokines retinol binding protein 4 and resistin." (PMID 35448889, 2022).
viral hepatitis (1 paper, 2022). An acute or chronic inflammation of the liver parenchyma caused by viruses. "Evidence suggests that acute hypervitaminosis A is associated with viral hepatitis, with elevated serum and liver concentrations of vitamin A and decreased serum retinol-binding protein 4 (RBP4)." (PMID 36531832, 2022).
α-synucleinopathy (1 paper, 2024). "Hub genes of the α-synucleinopathy-associated modules included RBP4, C1orf70 (TMEM240), and SCARF2, which have been previously implicated in PD." (PMID 38995454, 2024).
cardiovascular disease (75 papers, 2009 to 2026). "Measuring RBP4 levels aids in identifying individuals at risk for metabolic and cardiovascular diseases, with changes in RBP4 levels reflecting intervention effectiveness." (PMID 40276651, 2025). "Experimental and clinical studies have confirmed a positive association between upregulated RBP4 and the incidence of cardiovascular diseases, including coronary artery disease, stroke, and hypertension." (PMID 40940776, 2025). "STRA6 is the RBP4 membrane receptor and circulating RBP4 levels are associated with cardiovascular disease." (PMID 41035698, 2025). "Beyond statistical associations, multiple lines of evidence establish RBP4 as an independent prognostic risk factor for cardiovascular disease." (PMID 40276651, 2025). "Previous studies have shown that circulating RBP4 levels are associated with BP and cardiovascular disease." (PMID 39698033, 2024). "RBP-4 is considered as an important risk factor for plaque formation in carotids and the development of cardiovascular diseases." (PMID 36902521, 2023). "In recent years, more studies have suggested that RBP4 is also closely associated with lipid parameters and cardiovascular disease." (PMID 35309061, 2022). "The association between RBP4 concentrations and cardiovascular disease has been investigated in several studies, yielding mixed results." (PMID 34419052, 2021). "The previous studies have showed that serum retinol binding protein 4 (RBP4) levels increase in metabolic disorders which are closely associated with cardiovascular diseases (CVD)." (PMID 34616228, 2021). "There is increasing data strongly supporting the fact that the serum level of RBP-4 is associated with cardiovascular disease as well as adverse cardiovascular outcomes." (PMID 32449048, 2020). "In our review, we summarized the current knowledge about RBP4 and its association with essential aspects of cardiovascular disease—lipid profile, intima-media thickness, atherosclerotic process, and diet." (PMID 32718041, 2020). "RBP4 appeared to have a mediating role in the association of 25(OH)D and multiple risk factors for cardiovascular diseases." (PMID 30186876, 2018). "Several studies even showed a protective role of RBP4 on vascular in the population with a high risk of cardiovascular diseases." (PMID 30186876, 2018). "High ROH and RBP4 serum concentrations have been linked to an increased intima-media thickness, an established surrogate marker for cardiovascular disease." (PMID 25119682, 2015). "The present study examined the relationship between serum level of RBP4 and various risk factors related to cardiovascular disease (CVD) in men and women." (PMID 23119072, 2012). "This »sterile inflammation« indicates that RBP4 may play a causative role in endothelial and vascular inflammation, potentially contributing to cardiovascular disease and diabetic microvascular complications." (PMID 40951890, 2025). "Intriguingly, RBP4 was also reported to function as a biomarker for cardiovascular diseases risk, suggesting a potential role of metabolic dysregulation of RBP4, which could be associated with advanced glycolysis rate in the RBP4+ tumor cells." (PMID 38913193, 2024). "RBP4 levels have been strongly associated with cardiovascular disease." (PMID 38129891, 2023). "Consequently, defects/mutations in RBP4 can cause a variety of conditions and diseases due to dysregulated retinoid homeostasis and cover embryonic development, vision, metabolism, and cardiovascular diseases." (PMID 35334893, 2022). "Elevation of serum RBP4 is known to be linked with various cardiovascular diseases." (PMID 33805189, 2021). "In fact, elevated RBP-4 levels were found to be a new risk factor for cardiovascular disease." (PMID 32449048, 2020). "Clinically, RBP4 is a marker for atherosclerotic-associated cardiovascular disease." (PMID 32947976, 2020).